CAT (catalase)
Diseases named in the same sentence as CAT in open-access papers (continued):
Sharing a sentence is not in itself a finding about the gene and the disease.
colon carcinoma (43 papers, 2009 to 2025). "However, reduced occurrence of antioxidant defense mechanisms, such as catalase, is linked to CD and colon cancer." (PMID 33322398, 2020). "In contrast, levels of peroxisomes and the activity of their key enzyme, catalase, as well as of two enzymes involved in the peroxisomal β-oxidation pathway, were shown to be significantly reduced in colon carcinoma." (PMID 41373547, 2025). "The reduced expression of pro‐inflammatory proteins along with ROS and subsequent elevation in catalase levels by 4‐PBA in colon cancer cell lines indicates a correlation between ER‐stress and inflammatory response." (PMID 40953838, 2025). "For instance, a Zn(II) complex tested against human colon cancer cells demonstrated cytotoxic effects by inhibiting CAT through mixed-type inhibition kinetics." (PMID 41256015, 2025). "The injection of Cd-O2/N2 atomized gas further significantly suppressed the expression of SOD1 (C-Blank and C-Control: p < 0.001; C-S-Blank: p < 0.05), SOD2 (C-Control: p < 0.05), and CAT (C-Blank and C-Control: p < 0.01) in the colon tumors of the CC mice." (PMID 38535948, 2024). "For example, Lactiplantibacillus plantarum Y44 and Lacticaseibacillus casei Shirota have been shown to enhance the antioxidant capacity of Caco-2 human colon cancer cells by increasing the activities of catalase and glutathione peroxidase." (PMID 39408975, 2024). "The effect of Cd-O2/N2 atomized gas on the expression levels of NOX1, SOD2, and CAT in the colon tumors of the CC mice with intestinal stents implanted in them was not statistically significant." (PMID 38535948, 2024). "FOXO members respond against oxidative stress via the transcriptional regulation of manganese superoxide dismutase and catalase gene expression in human colon carcinoma cells." (PMID 37535699, 2023). "Conversely, silencing of CAT leads to maintenance of colon cancer cells in a senescent state, thereby inhibiting tumor progression." (PMID 37313408, 2023). "CAT activity is increased in colon tumors due to the ability of this enzyme to reduce ROS levels in tumor cells, but this also activates leukocytes in the tumor microenvironment." (PMID 37313408, 2023). "So far, elevated expression of total CAT protein level has been found on the cell surface of tumor cells such as gastric cancer, skin cancer, colon cancer, and chronic myeloid leukemia." (PMID 35392238, 2022). "Altogether, these data showed that, in contrast to CAT and GPx-1, HO-1 expression was downregulated upon the induction of senescence in colon cancer cells." (PMID 36230727, 2022). "Silencing of antioxidative enzymes such as catalase (CAT) or glutathione peroxidase-1 (GPx-1) maintained colon cancer cells in a senescent state." (PMID 36230727, 2022). "The nano-extract increased the relative quantities of the total CAT isoenzymes significantly (P≤0.05) when compared to colon cancer induced group and restored their values to normal levels in all nano-extract treated groups." (PMID 34711004, 2021). "As regard to the quantitative level, it was found that the relative quantities of the total CAT types decreased significantly (P≤0.05) in colon cancer induced group as compared to control group." (PMID 34711004, 2021). "At the quantitative level, it was found that the relative quantities of the total CAT types decreased significantly (P≤0.05) in AOM induced colon cancer group as compared to control group." (PMID 32458646, 2020). "A selective colon cancer cell therapy was effectively achieved with catalase-mediated intra-cellular heterogeneous Fenton reactions triggered by cellular uptake of SnFe2O4 nanocrystals." (PMID 30410055, 2018). "Our data showed that droxinostat induced oxidative stress and ROS production in colon cancer cells, which is supported by the decreased expression of catalase, SOD1 and SOD2 with droxinostat treatment." (PMID 30065760, 2018).
colon carcinoma (continued). "Low levels of CAT expression correlate with a high production of ROS, and oral administration of catalase producing Lactoccosus lactis is beneficial in the context of chemically induced colon cancer and inflammation in mice." (PMID 39779288, 2025). "In colon carcinoma, the inhibition of catalase to enhance intracellular levels of free radicals leads to cell death, which might provide a new concept to the clinical therapy of drugs." (PMID 37372967, 2023). "They observed that triflumuron induced the generation of reactive oxygen species, followed by lipid peroxidation, due to increased levels of malondialdehyde, a pro-oxidative parameter, and activating the antioxidant enzymes, catalase, and superoxide dismutase, in human colon tumor cells (HCT 116)." (PMID 36908412, 2023). "Interestingly, when we silenced CAT and GPx-1 in senescent colon cancer cells with specific siRNAs and treated these cells with hemin, we observed that the expressions of cyclins, especially cyclin B, were reduced." (PMID 36230727, 2022). "In the nano-extract simult- and post-treated groups, nano-extract caused significant (P≤0.05) increase in TAC level and activities of CAT and GPx associated with lowering concentrations of LPO and TPC as compared to colon cancer induced group and restored their levels to normalcy." (PMID 34711004, 2021). "The lowest similarity index (SI%) values were noticed with electrophoretic protein (SI=71.43%), lipid (SI=0.00%) and calcium (SI=75.00%) moieties of protein patterns, catalase (SI=85.71%), peroxidase (SI=85.71%), α-esterase (SI=50.00%) and β-esterase (SI=50.00%) isoenzymes in colon cancer group." (PMID 32458646, 2020). "Although treatment with C. tiglium nano-extract increased the relative quantities significantly (P≤0.05) in all nano-extract treated groups with respect to AOM induced colon cancer group, quantities of the total CAT types restored to normal values in the nano-extract post-treated group." (PMID 32458646, 2020). "LAB are generally CAT-negative; however, de LeBlanc and colleagues proved that a CAT-producing Lactococcus slactis could prevent 1,2-dimethylhydrazine-induced colon cancer in mice." (PMID 28534820, 2017). "Heterologous expression of nonheme catalase in Lactobacillus lactis improved the antioxidant status and alleviated the risk of 1,2-dimethyl hydrazine induced colon cancer." (PMID 25050329, 2014). "In a previous study, we found that exposure of LS174T human colon cancer cells to DPI (250 nM) or DTI (10 μM) for 24 h produced a significant (>80%) inhibition of NOX1 mRNA expression without altering the expression levels of the antioxidant enzymes catalase or glutathione peroxidase." (PMID 34829628, 2021). "Further, a more recent study found that exopolysaccharides (EPS) derived from the probiotic Lactobacillus acidophilus increase the antioxidant enzymes (SOD, CAT, and GPx) concentrations in DMH-induced colon cancer model." (PMID 39201713, 2024). "Further support for these findings comes from studies involving Lactobacillus plantarum administered in vitro to DMH-induced colon cancer cells, which similarly increased antioxidant enzyme activity, including SOD, CAT, and GST." (PMID 39201713, 2024). "Fortunately, treatment of colon cancer-modeled rats with LME resulted in a significant decompensation of the depleted colon GSH content, and upregulated the activity of colon CAT, GPx, and SOD." (PMID 36294905, 2022). "Here, we demonstrated that, upon the induction of senescence with IRINO, the expression of CAT and GPx-1, enzymes that utilize H2O2, was strongly upregulated in colon cancer cells." (PMID 36230727, 2022). "LLEFE was able to significantly (P < 0.05) upregulate SOD1, CAT, and GSH and significantly (P < 0.05) downregulate PI3K, Akt, and mTOR expression in HT-29 colon cancer cells." (PMID 35586809, 2022).
colon carcinoma (continued). "LLEFE increased the LDH level in an HT-29 colon cancer cell culture medium; also increased the superoxide dismutase (SOD), catalase (CAT) activities, and glutathione (GSH) level in HT-29 cells; and decreased the malondialdehyde (MDA) level." (PMID 35586809, 2022). "Treatment of ruthenium-phloretin significantly elevated expressions of SOD, CAT, and GSH in colon cancer cells, probably by stimulating the ROS to instigate the apoptotic events." (PMID 32566099, 2020). "As an antioxidant, luteolin acted as a ROS scavenger in colon cancer cells (HT-29) and induced superoxide dismutase (SOD) and catalase (CAT) antioxidant enzyme expression." (PMID 33217901, 2020). "The results are consistent with previous studies that chemopreventive agents protect against colon cancer via increasing SOD and CAT activities." (PMID 31509964, 2019). "Human colon carcinoma cells were shown to exhibit a decreased or even absence of expression of some peroxisomal proteins, such as catalase and acyl-CoA oxidase enzymes, and some membrane proteins." (PMID 41373547, 2025). "When colon cancer cells were treated with fermentation supernatants derived from raw and roasted pistachios, they displayed increased caspase-3 activity, decreased H2O2-induced DNA damage, and increased CAT, SOD2, and GSTP1 gene expression mRNA levels." (PMID 40699792, 2025). "Interestingly, the oral administration of Lactococcus lactis, a catalase-producing bacterium, prevented 1,2 dimethylhydrazine (DMH)-induced colon cancer." (PMID 39201713, 2024). "Taken together, these data suggest that the silencing of antioxidative enzymes—HO-1, CAT, and GPx-1—maintains colon cancer cells in a non-proliferating, epithelial state with increased mechanisms of DNA protection." (PMID 36230727, 2022). "In the present study, we showed that the induction of senescence in colon cancer cells led to the upregulation of two enzymes involved in H2O2 utilization, catalase, and glutathione peroxidase-1 but the downregulation of heme oxygenase-1, heme degrading enzyme." (PMID 36230727, 2022). "Similarly, thymol had a promising protective efficacy, revealing a chemopreventive effect against colon cancer observed by the increase in GST, GSH, SOD and CAT levels, in addition to inhibiting oxidative stress." (PMID 34305611, 2021). "The implantation of intestinal stents inhibited the expression of Superoxide Dismutase 1 (SOD1) in the colon tumors of the CC mice, with no evident effects on the expression levels of NOX1, SOD2, and Catalase (CAT) enzymes." (PMID 38535948, 2024).
periodontitis (43 papers, 2013 to 2026). An acute or chronic inflammatory process that affects the tissues that surround and support the teeth. "The purpose of this study was to investigate the effect of resveratrol in a rat model of experimental periodontitis by assessing alveolar bone loss along with catalase and glutathione peroxidase mRNA expression and enzymatic activity in gingival tissue." (PMID 41395982, 2025). "Enzymatic antioxidants associated with periodontitis include catalase (CAT), glutathione reductase (GR), and total antioxidant capacity." (PMID 39554809, 2024). "Several studies have shown that decreased activity of enzymatic antioxidants such as superoxide dismutase (SOD) and catalase (CAT) is associated with periodontitis." (PMID 37501927, 2023). "Some studies suggested decreased activities of enzymatic antioxidants, like SOD and CAT, are associated with periodontitis, whereas others showed increased activities of enzymatic antioxidants among people with periodontitis as a protective reaction." (PMID 29180965, 2017). "Moreover, a wealth of research has shown that periodontitis is associated with diminished activity of crucial enzyme antioxidants, including catalase (CAT) and superoxide dismutase (SOD)." (PMID 40710159, 2025). "Based on this evidence, the present study was conducted to determine the effect of resveratrol on periodontal tissue damage in a rat experimental periodontitis model by evaluating alveolar bone loss and Catalase (E.C: 1.11.1.6) and GPx (E.C: 1.11.1.9) mRNA levels and activities in gingival tissue." (PMID 41395982, 2025). "This study is the first to evaluate the effect of resveratrol administration on gingival tissue mRNA levels and enzyme activities of CAT and GPx1 in a rat experimental periodontitis model simultaneously." (PMID 41395982, 2025). "In the literature, studies evaluating the use of antioxidants and their impact on catalase levels in experimental periodontitis models have reported notable findings." (PMID 41395982, 2025). "Nanozymes, with intrinsic enzyme-mimicking activity, can catalyze reactions like peroxidase(POD) or CAT, aiding in the degradation of harmful biomolecules and modulation of oxidative stress, particularly in the management of periodontitis." (PMID 39554809, 2024). "A previous clinical trial found that the serum levels of catalase in patients with concomitant periodontitis and diabetes mellitus were lower than individuals with and without periodontitis." (PMID 38149100, 2023). "In contrast to our result, clinical studies reported that antioxidant levels of SOD, CAT, and GPx were decreased significantly in diabetic patients with periodontitis as compared to controls." (PMID 35592526, 2022). "GSH, SOD, and CAT levels in the high-dose DhHP-6 group were significantly higher than those in the periodontitis group." (PMID 36546940, 2022). "The serum levels of GSH, SOD, and CAT in rats with periodontitis were lower than those in untreated rats." (PMID 36546940, 2022). "Similar to the current study, increase levels of MDA, SOD, and CAT in experimentally induced periodontitis have been reported as compared to control group." (PMID 35592526, 2022). "The main enzymatic antioxidants which have been widely studied in the gingival fluid, saliva and blood serum of patients with periodontitis are superoxide dismutase, glutathione peroxidase and catalase." (PMID 33578659, 2021). "Catalase level reductions were detected in saliva of individuals with periodontitis when compared to healthy individuals." (PMID 32267380, 2020). "This study aims to investigate the association of polymorphisms C677T in MTHFR (rs1801133) and −149C→T in DNMT3B (rs2424913), as well as the methylation profiles of MTHFR, miR-9-1, miR-9-3, SOD1, and CAT with periodontitis." (PMID 32267380, 2020).
periodontitis (continued). "Periodontitis patients exhibited significant decrease in the activities of catalase, TAOC, GR and TG, cholesterol, LDLc, glucose, HDLc, uric acid levels in plasma samples in comparison with healthy subjects." (PMID 31640685, 2019). "Moreover, periodontitis was associated with an enhanced production of TLR2, MyD88 and TGFβ, as well as higher activities of SOD and catalase antioxidant enzymes in the adipose tissue." (PMID 42037322, 2026). "Within the limitations of this study, it can be concluded that resveratrol has a modulatory effect on antioxidant defense mechanisms in experimental periodontitis, reflected by changes in enzymatic activities and gene expression of key antioxidants such as catalase and GPx." (PMID 41395982, 2025). "Oxidative stress in periodontitis involves the generation of reactive oxygen species, such as superoxide anion and hydrogen peroxide, overwhelming antioxidant defenses, such as superoxide dismutase and catalase." (PMID 39597014, 2024). "The results showed an increase in oxidative stress-related molecules SOD and CAT in the gingival tissue of the rats in the treatment group in gingivitis and periodontitis rat models treated with Eucommia extracts by topical smearing and intragastric administration." (PMID 35932002, 2022). "However, the microRNA expression as well as antioxidant proteins, such as superoxide dismutase and catalase, are altered in periodontitis patients' gingival tissue cells and saliva." (PMID 32267380, 2020). "This study is the first to compare the serum and salivary levels of the antioxidants (TAC, SOD, catalase, and glutathione levels) within the groups of healthy subjects, chronic periodontitis patients, and ischemic heart disease patients with or without periodontitis." (PMID 28781595, 2017). "Gingival activities of specific antioxidants like SOD, CAT, and GPx could be increased by smoking among people with periodontitis, and these changes were considered as a protective or adoptive mechanism." (PMID 29180965, 2017). "Meanwhile, in rats with glucocorticoid-induced osteoporosis submitted to periodontitis, ATV at 27 mg/kg decreased bone loss, reduced myeloperoxidase (MPO), TNF-α, IL-1β, IL-6, and IL-8, and increased IL-10, glutathione (GSH), superoxide dismutase (SOD), and catalase (CAT) levels." (PMID 39476053, 2024). "Therefore, the main objective of this study was to investigate the association between the MTHFR rs1801133 and the DNMT3B rs2424913 polymorphisms, and methylation profiles from MTHFR, miR-9-1, miR-9-3, superoxide dismutase (SOD1), and catalase (CAT) genes with periodontitis." (PMID 32267380, 2020). "The catalase may be a potential drug target to aid in the prevention of periodontitis." (PMID 30894650, 2019). "Additionally, our study illustrated that KatA of Aa VT1169 was important for the growth of both Pg and Aa VT1169, implying that catalase might be a promising drug target to prevent periodontitis." (PMID 30894650, 2019). "Patients with periodontitis show elevated levels of OS biomarkers, such as MDA and H2O2, which are correlated with reduced activity of antioxidant enzymes like SOD and CAT." (PMID 40422642, 2025). "It has also been indicated that 100 mg/kg/day of crocin attenuated periodontitis‐induced cardiac injury by the mitigation of MDA and enhancement of GSH, superoxide dismutase (SOD), catalase (CAT) in rats." (PMID 37537722, 2023). "The group of smokers with periodontitis had the highest level of MDA and the lowest activity of SOD, CAT and GSH-Px in gingival tissues compared to the control group of non-smokers with healthy periodontium." (PMID 35153810, 2021). "Here we demonstrated that rats with periodontitis showed a significant reduction in both SOD and CAT levels, when compared to naive rats." (PMID 31682614, 2019). "In the present study periodontitis induction resulted in a significant (P < 0.05) reduction of SOD and CAT levels in gingival tissue, when compared with naive group." (PMID 29249988, 2017).